MYBL2 (MYB proto-oncogene like 2)
Description:
Transcription factor involved in the regulation of cell survival, proliferation, and differentiation. Transactivates the expression of the CLU gene.
Synonyms: B-Myb; BMYB
Tractability: PROTAC: UniProt records ubiquitination sites on it; ubiquitination databases record sites on it.
Gene: Protein-coding gene on chromosome 20 (43,667,019 to 43,716,495, forward strand). Ensembl gene ENSG00000101057.
Subcellular location: Nucleus
Subcellular location (Human Protein Atlas): Nucleoplasm; Cytosol
Pathways (Reactome):
Cell Cycle: Polo-like kinase mediated events; Transcription of E2F targets under negative control by p107 (RBL1) and p130 (RBL2) in complex with HDAC1
Gene expression (Transcription): TFAP2A acts as a transcriptional repressor during retinoic acid induced cell differentiation
Gene Ontology:
Molecular function: DNA-binding transcription activator activity, RNA polymerase II-specific; protein binding; RNA polymerase II cis-regulatory region sequence-specific DNA binding; sequence-specific double-stranded DNA binding
Biological process: positive regulation of transcription by RNA polymerase II; mitotic cell cycle
Cellular component: nucleoplasm; nucleus; RNA polymerase II transcription regulator complex; Myb complex
Genetic constraint (gnomAD): Loss-of-function variants: 28 observed, 77.41 expected, observed/expected ratio (o/e) 0.36, 90% interval 0.27 to 0.5. The upper end of that interval is the gene's LOEUF score, 0.5, which puts it in group 2 of 6, group 1 being the genes least tolerant of losing a copy. Missense variants: 735 observed, 915.86 expected, observed/expected ratio (o/e) 0.8, 90% interval 0.75 to 0.85. Synonymous variants: 378 observed, 370.61 expected, observed/expected ratio (o/e) 1.02, 90% interval 0.94 to 1.11.
Homologues: Orthologues: chimpanzee MYBL2 (99% identical), macaque MYBL2 (98% identical), dog MYBL2 (92% identical), guinea pig MYBL2 (89% identical), rabbit MYBL2 (89% identical), pig MYBL2 (88% identical), rat Mybl2 (87% identical), mouse Mybl2 (85% identical), tropical clawed frog mybl2 (55% identical), zebrafish mybl2b (49% identical). Paralogues in human: MYBL1 (40% identical), MYB (38% identical), SNAPC4 (19% identical), CDC5L (19% identical), DMTF1 (13% identical), TTF1 (9% identical).
Diseases named in the same sentence as MYBL2 in open-access papers:
MYBL2 is named in the same sentence as 113 diseases in open-access papers, as found by Europe PMC text mining. Sharing a sentence is not in itself a finding about the gene and the disease. The quoted sentences say what the papers report.
breast cancer (84 papers, 2003 to 2025). A primary or metastatic malignant neoplasm involving the breast. "Aberrant MYBL2 overexpression has been implicated in tumor proliferation, invasion, and poor prognosis across multiple malignancies, including breast cancer, colorectal cancer, and glioma." (PMID 40432915, 2025). "Breast cancer with high MYBL2 expression is associated with poor prognosis and a basal-like subtype." (PMID 38835346, 2024). "The MYBL2 S427G variant has been reported to be associated with an increased risk of basal-like breast cancer in the African American population; however, the specific mechanism has not been clarified." (PMID 37144133, 2023). "This is consistent with the population association analysis results that MYBL2 AS-related genetic variants can reduce the risk of breast cancer." (PMID 37144133, 2023). "We then delimited the MYBL2 gene, which finally resulted in 199 breast cancer associated SNPs potentially affecting AS in MYBL2 in CancerSplicingQTL." (PMID 37144133, 2023). "MYBL2 is essential to regulate cell proliferation, differentiation, and DNA repair, and its overexpression is associated with shorter overall survival in breast cancer patients." (PMID 35685832, 2022). "Cluster 3 (CCNE1 and MYBL2) has the same pattern of expression as Clusters 1 and 2 in breast cancer patients and is associated with regulation of cell cycle phase transition GO term." (PMID 31260503, 2019). "We found that B-Myb (encoded by MYBL2) binds the A3B promoter, causing transactivation, and this is responsible for the C-to-T transitions and DNA hypermutation in breast cancer cells." (PMID 28276478, 2017). "In our study, we evaluated the association between an MYBL2-adjacent SNP and disease-free survival in breast cancer patients." (PMID 28276478, 2017). "Included in this region were STK15, which has recently been suggested to be a candidate low-penetrance tumor susceptibility gene in breast cancer and MYBL2, which has been shown to be overexpressed along with STK15 and ZNF217 in prostate cancer." (PMID 17428335, 2007). "For example, Ki-67, STK15, Survivin, Cyclin B1, and MYBL2 have all been associated with breast cancer proliferation; Stromelysin 3 and Cathepsin L2 have been associated with invasion; and ER, PR, Bcl2, and SCUBE2 have been associated with responsiveness to Estrogen." (PMID 29848291, 2018). "If overexpression of MYBL2, as well as A3B, is associated with breast cancer progression, polymorphisms in the expression quantitative trait loci (eQTL) that are associated with MYBL2 mRNA expression would be expected to be significantly associated with disease outcome." (PMID 28276478, 2017). "Hence, we investigated whether MYBL2 expression correlates with mutation load in cancers other than breast cancer using 33 cancer types and mutation load data from TCGA." (PMID 28276478, 2017). "The published article titled “MYBL2 is targeted by miR-143-3p and regulates breast cancer cell proliferation and apoptosis” has been retracted from Oncology Research, Vol." (PMID 40109855, 2025). "MYBL2 knockout markedly reduced CDCA8 mRNA expression and protein secretion in breast cancer tissues, while MYBL2 overexpression significantly upregulated CDCA8 gene expression and protein level." (PMID 38961953, 2024). "have demonstrated that elevated MYBL2 expression correlates with metastasis, poorer disease-free survival, and shorter overall survival in breast cancer, highlighting how increased MYBL2 expression contributes to the disease’s enhanced invasiveness." (PMID 39139556, 2024). "NOTCH3 is very weakly expressed in breast cancer cells, which prevents tumor occurrence through HeyL-mediated inhibition of Mybl2 (an important cell cycle regulator), and is related to good prognosis." (PMID 38164285, 2024). "The MBY gene family, MYBL2, also known as B-Myb, is highly expressed in several solid tumors, including breast cancer, non–small-cell lung cancer, and colorectal cancer." (PMID 38565963, 2024).
breast cancer (continued). "Previous studies have shown that MYBL2 is highly expressed in cancers such as ovarian cancer and breast cancer and affects the prognosis of patients." (PMID 36685007, 2023). "The expression landscape of MYBL2 splice isoforms in breast cancer was next analysed on the TSVdb platform." (PMID 37144133, 2023). "Rising evidence has suggested that MYBL2 is frequently overexpressed in breast cancer and other solid tumors, and it has a positive correlation with the poor prognosis of patients with solid tumor." (PMID 36814821, 2023). "In breast cancers, MYBL2 can transactivate the MYC and CCNB1 genes by binding their promoters and expediting the cell cycle of cancer cells." (PMID 36814821, 2023). "Altogether, these data, show that Notch3, in breast cancer cells, induces a strong expression of HeyL that leads to downregulation of Mybl2, which leads to decreased proliferation." (PMID 36854682, 2023). "In this study, biological information analysis predicted the expression of ABRACL and MYB proto-oncogene-like 2 (MYBL2) in breast cancer tissues and their possible relationship." (PMID 35341461, 2022). "Subsequently, GEPIA2 database revealed that MYBL2 expression gained a huge growth in breast cancer tissues as well." (PMID 35341461, 2022). "All findings suggest that overexpression of MYBL2 partially reverses the regulatory effects of ABRACL knockdown on the proliferation of breast cancer cells." (PMID 35341461, 2022). "MYBL2 is positively regulated in eight datasets of lung cancer and in two datasets of breast cancer." (PMID 36101460, 2022). "Recent studies reported genetic alterations in MYBL2 gene locus, and contributes to tumorigenesis in colorectal, prostate and breast cancer." (PMID 36494680, 2022). "With the application of RT-qPCR and western blot, the mRNA and protein expression of ABRACL and MYBL2 in breast cancer cell lines were assessed." (PMID 35341461, 2022). "In breast cancer, the increased expression of MYBL2 regulates the changes in downstream microRNAs and single nucleotides in the coding regions of other genes." (PMID 36133745, 2022). "Overexpression of MYBL2 correlates with poor prognosis in numerous cancers, including breast cancer." (PMID 35200555, 2022). "MYBL2 is upregulated in many cancers, such as breast cancer, hepatocellular carcinoma, lung cancer, and colorectal cancer, and upregulated expression of MYBL2 is associated with poor prognosis in patients with cancer." (PMID 35664780, 2022). "Our experiments revealed that overexpression of MYBL2 did partially restore the malignant biological behaviors as well as the EMT process in breast cancer cells after ABRACL knockdown." (PMID 35341461, 2022). "The aberrant expression or dysfunction of MYBL2 has been validated in a variety of cancers including adult leukemia, breast cancer, prostate cancer, ovarian cancer, liver cancer, and lung cancer." (PMID 34568071, 2021). "For example, a high level of B-Myb/MYBL2 expression in breast cancer is a clinically useful predictor of tumor recurrence and decreased patient survival." (PMID 32295830, 2020). "MYBL2 expression is upregulated in several cancers, including breast cancer, reportedly with the highest expression in basal-like breast cancer, and lowest in normal-like and luminal A type breast cancer." (PMID 30833639, 2019). "Because MYBL2 expression correlates with poor prognosis of breast cancer patients, it has been utilized as an independent biomarker to predict breast cancer recurrence." (PMID 28276478, 2017). "AURKA, BIRC5, CCNB1, MKI67 and MYBL2 are well characterized genes involved in breast cancer proliferation." (PMID 22046260, 2011). "Among the larger modules, we identified one associated with the cell-cycle (CDC2, CDC20, MYBL2, MAD2L1) consistent with many other studies showing the importance of cell-cycle genes in breast cancer prognosis." (PMID 20673354, 2010).
breast cancer (continued). "This study analyzed the expression of MYBL2 across various tumors and found that MYBL2 was significantly upregulated in 20 different cancer types, consistent with previous findings in breast cancer, hepatocellular carcinoma, cervical squamous cell carcinoma, and prostate cancer." (PMID 40432915, 2025). "Although multiple SNPs associated with breast carcinogenesis have been found, the association of MYBL2 AS-related SNPs with breast cancer susceptibility has not been explored to date." (PMID 37144133, 2023). "The results showed that the expression levels of both E2F8 and MYBL2 were upregulated in female cancers compared to adjacent tissues, such as breast cancer (BRCA), ovarian cancer (OV), and cervical squamous cell carcinoma and endocervical adenocarcinoma (CESC)." (PMID 36814821, 2023). "Interestingly, MYBL2 had higher expression levels in both luminal A and basal-like breast cancer tissues than in adjacent tissues." (PMID 36814821, 2023). "Similar results were observed in breast cancers with high expression of MYBL2." (PMID 36814821, 2023). "Given that the expression of ABRACL and MYBL2 was upregulated in breast cancer cells, the following experiments were conducted to verify whether there was a link between them." (PMID 35341461, 2022). "Furthermore, MYBL2 stimulates the transcription of target genes and promotes the entry of breast cancer into the S and M phases of the cell cycle, cell proliferation, migration, and invasion." (PMID 35341461, 2022). "Importantly, MYBL2 knockdown imparted suppressive effects on the proliferative ability of breast cancer cells." (PMID 35341461, 2022). "Here, we investigated whether MYBL2 overexpression could stimulate the proliferative ability of breast cancer cells." (PMID 35341461, 2022). "Results revealed that ABRACL and MYBL2 were highly expressed in breast cancer tissues and cells." (PMID 35341461, 2022). "Previous findings confirmed that ABRACL knockdown could inhibit the malignant behaviors and EMT of breast cancer cells and was transcriptionally regulated by MYBL2." (PMID 35341461, 2022). "The expression of key markers associated with proliferation (MKI67, PCNA, CCNB1, MYBL2, BUB1, CCND1), apoptosis (BCL2, CASP7, CASP8, CASP9, CASP3, BAX, APAF1), differentiation (CDH1, CD24, EPCAM, ESR1, NGFR, RUNX1), and breast cancer stemness (CD44, ITGA6, DNER, ALDH1A3, ABCG2, PROCR) was assessed." (PMID 35183258, 2022). "MYBL2 is highly expressed in more aggressive subtypes of breast cancer, such as TNBC." (PMID 34675301, 2021). "Interestingly, some genes involved in these processes and signal pathways, such as CCNB1, CDK1, CHEK2, and MYBL2, have been widely reported as oncogenes and used in the clinical diagnosis for breast cancer patients." (PMID 34646403, 2021). "Rs2070235, which results in a missense variant (Ser > Gly) of MYBL2 protein, was reported to be associated with an increased risk of breast cancer, but not with the incidence of acute myeloid leukemia." (PMID 34568071, 2021). "Finally, MYB, MYBL1 and MYBL2 were reported to be upregulated by ESR1 signaling in breast cancer cells." (PMID 30833639, 2019). "Quantitative analysis of transcript abundance among the three sub-populations of OR genes confirmed that the genes associated with breast cancer cell proliferation (MKI67, AURKA, BIRC5, CCNB1, MYBL2) were significantly abundant in sub-population I with OR2B6 upregulation." (PMID 31551495, 2019). "Similar to MYB, both MYBL1 and MYBL2 are upregulated by ESR1 signaling in breast cancer cells." (PMID 30833639, 2019). "MYBL2 is overexpressed in hepatic cancer, breast cancer and bladder cancer." (PMID 31756170, 2019).
breast cancer (continued). "In particular, the predicted effect on MYBL2 could be validated, and a synergistic effect of paclitaxel and doxorubicin could be demonstrated in the breast cancer cell lines SKBR3 and MCF-7." (PMID 24349128, 2013). "LUMB breast cancers are characterized by expression of HR along with HER2 associated genes (i.e., ERBB2 and GRB7) and a cell proliferation pattern designated by expression of MK167, CCNBI and MYBL2." (PMID 20492711, 2010). "For example, hsa-miR-29b and its predicted MYBL2 target are deregulated in breast cancer." (PMID 17971223, 2007). "Indeed Mybl2 is an important regulator of cell cycle and has an important role in breast cancer." (PMID 36854682, 2023). "However, the exact function of MYBL2 in basal-like breast cancer needs to be clarified." (PMID 36814821, 2023). "Our experiments disclosed that MYBL2 could be widely found in breast cancer cells." (PMID 35341461, 2022). "Although the MYBL2 gene encoding the B-Myb protein is altered in only 4% of breast cancers, increased levels of expression of this gene occur more frequently, particularly in basal-like and triple-negative (ER-, PR-, HER2-) breast cancers that generally have a poor prognosis." (PMID 32295830, 2020). "Indeed, MYBL2 is one of a small number of genes included in the Oncotype DX gene expression test that is widely used to predict clinical outcomes and plan treatment for patients with breast cancer." (PMID 32295830, 2020). "Previous investigation had proved that MYBL2 played a role in proliferation, invasion and migration through the regulation of CDCA8 in breast cancer cell." (PMID 38961953, 2024). "The metastasis-related gene MMP11 and proliferation-related genes BIRC5, MYBL2, MKI67 (Ki67), AURKA (STK15), CCNB1, and ERBB2 (HER2) from the Oncotype DX gene set exhibit significant up-regulation in tumor samples of breast cancer (BRCA)." (PMID 38254834, 2024). "Only MMP11, MYBL2, SFRP1, and UBE2C identified in our study are also featured together as biomarkers in the PAM50 breast cancer 50 gene panel." (PMID 39596491, 2024). "In breast cancer, eight winning TFs (ZBTB16, KLF2, KLF4, NR2F1, EGR1, FOSB, EPAS1, and GPRASP1) can form a coregulatory network, and three other winning TFs (MYBL2, FOXM1, and TAL1) can form another coregulatory network." (PMID 36101460, 2022). "The evidences showed in this section note that MYBL2 overexpression reverses the regulatory effects of ABRACL knockdown on the relative invasion and migration rate, as well as EMT process of breast cancer cells." (PMID 35341461, 2022). "In view of all that has been discussed so far, we can conclude that ABRACL can be transcriptionally regulated by MYBL2 to promote the proliferative ability, relative migration rate, invasive ability, as well as EMT process of breast cancer cells." (PMID 35341461, 2022). "Particularly, among the top 14 TFs, four (SR1, FOXA1, FOXC1, MYBL2) were among the TFs of the PAM50 gene signature (p = 1.46E-7, hypergeometric test), further indicating their role in regulatory mechanisms of breast cancer subtypes." (PMID 33558504, 2021). "MYBL2 (MYB proto-oncogene like 2) is included in the family of MYB transcription factors and was overexpressed in breast cancer." (PMID 34093635, 2021). "PKMYT1, MYBL2, and CDC20 participate in GO terms of the most upregulated KEGG processes and are involved in the development of breast cancer." (PMID 34834441, 2021). "A recent analysis of highly aneuploidy breast cancers in TCGA found overexpression of three transcriptional regulators, E2F1, MYBL2, and FOXM1." (PMID 32380981, 2020). "The elevated expression of IBSP, COL11A1, MYBL2 and UBE2C in breast cancer has previously been reported to directly correlate with tumor progression." (PMID 27359054, 2016). "The expression of MYBL2, HOXC13, and E2F8 was verified by qRT-PCR assay in breast cancers." (PMID 36814821, 2023).